SHH (sonic hedgehog signaling molecule)
Diseases named in the same sentence as SHH in open-access papers (continued):
Sharing a sentence is not in itself a finding about the gene and the disease.
hyperthyroidism (1 paper, 2024). Overactivity of the thyroid gland resulting in overproduction of thyroid hormone and increased metabolic rate. "Thus, it seems possible that similar mechanisms (T3 → TRβ/RXRα → HLF → HIF-1α → EPO and T3 → SHH → BMP-4 → BFU-E) may lead to increased erythropoiesis in human and feline hyperthyroidism and may explain the presence of erythrocytosis observed in this disease." (PMID 39518858, 2024).
intellectual disability syndromes (1 paper, 2013). "This subunit may regulate transcription of targets of the Wnt signaling pathway and SHH signaling pathway relevant for neurodevelopment and intellectual disability syndromes." (PMID 24007566, 2013).
invasive carcinoma (1 paper, 2019). A carcinoma that is not confined to the epithelium, and has spread to the surrounding stroma. "In addition, we analyzed data from recently published large-scale studies of gene expression in human invasive carcinoma to assess the association of SHH expression with the molecular subtypes and patient survival." (PMID 31036156, 2019). "We found that the methylation of the SHH gene, especially in the CpG shore of the promoter region, was significantly increased in the basal subtype of human invasive carcinomas compared to that in benign urothelia." (PMID 31036156, 2019).
keloid (1 paper, 2023). An irregularly shaped, elevated mark on the skin caused by deposits of excessive amounts of collagen during wound healing. "Furthermore, we found that SHH protein is widely expressed in keloids and surrounding dermal tissues." (PMID 38062202, 2023). "Because GLI1-inducing signals were upregulated in three different keloid-derived stem-like cells (KNS, KMS and KCS), SHH may be a major inducer of GLI1 in keloids." (PMID 38062202, 2023). "We found that the secretion of SHH and expression of GLI1 and its target genes are high at the keloid margins, where cell proliferation is very active." (PMID 38062202, 2023). "Although we did not provide a mechanism as to why SHH expression is increased in keloid tissues and by what mechanism activation of SHH signaling alters properties of stem like cells, our results suggest that the HH-GLI1 pathway is involved in the pathogenesis of keloids." (PMID 38062202, 2023). "The expression of PTCH1 was enhanced in GLI1-upregulated keloid-derived stem-like cells but not in fibroblasts from keloid tissues, suggesting that the response to SHH differs between mature fibroblasts and stem-like cells." (PMID 38062202, 2023).
kidney rhabdoid tumours (1 paper, 2015).
laurin-Sandrow syndrome (1 paper, 2021). Laurin-Sandrow syndrome (LSS) is characterized by complete polysyndactyly of the hands, mirror feet and nose anomalies (hypoplasia of the nasal alae and short columella), often associated with ulnar and/or fibular duplication (and sometimes tibial agenesis). "Both duplications do not include the ZRS and duplications of SHH itself have not been described to cause Laurin–Sandrow syndrome." (PMID 34159400, 2021). "The mirror-image polydactyly of individual I11 shows striking phenotypic overlap with Laurin–Sandrow syndrome, which is caused by duplications of the SHH regulator ZRS, positioned in intron 5 of LMBR1 on chr7p36.3, resulting in ectopic expression of SHH in the embryonic limb." (PMID 34159400, 2021).
lentivirus infection (1 paper, 2013). Virus diseases caused by the Lentivirus genus. "In summary, we investigated spatiotemporal expression of SHH and FAK Tyr397, and the function of SHH in osteoblasts by using a shFAK lentivirus infection model." (PMID 24124594, 2013).
leukoencephalopathies (1 paper, 2018). "We showed a reduction of mutant cDNA and perturbation of SHH signaling from patient‐derived cell lines; furthermore, analysis of human brain gene expression provides evidence that DDX59 is enriched in oligodendrocytes and might act within pathways of leukoencephalopathies‐associated genes." (PMID 29127725, 2018).
Lujan syndrome (1 paper, 2019). "Previous studies have shown that MED12 mutations in FG and Lujan syndromes disrupt a mediator‐imposed constraint on GLI3‐dependent SHH signaling." (PMID 30729724, 2019). "Increased transcript levels for SHH‐signaling genes have been reported in cell lines from patients with FG and Lujan syndrome." (PMID 30729724, 2019).
lung diseases (1 paper, 2017). "The precise mechanisms that Fstl1 regulates ASM and VSM formation, if and how Fstl1 regulates some important signaling pathways, such as BMP, SHH, WNT and FGF, during lung SM development and SM-related lung diseases including pulmonary artery hypertension, are actively pursued in our laboratories." (PMID 28574994, 2017).
Lynch syndrome (1 paper, 2014). An autosomal dominant hereditary neoplastic syndrome characterized by the development of colorectal carcinoma and a high risk of developing endometrial carcinoma, gastric carcinoma, ovarian carcinoma, renal pelvis carcinoma, and small intestinal carcinoma. "Whole-genome DASL-based gene expression profiling based on 18.6 k genes identified 349 significantly deregulated genes with up-regulation of e.g. PTPRH, BIRC3, SHH and TNFRSF6B in Lynch syndrome tumors." (PMID 24848881, 2014).
Miscarriage (1 paper, 2024). A pregnancy that ends at a stage in which the fetus is incapable of surviving on its own, defined as the spontaneous loss of a fetus before the 22th week of pregnancy. "There are 16 protein-coding genes located in this region, among them, expression of the SHH gene was confirmed as impaired in the villus of recurrent miscarriages which means that dysfunction of SHH might link to miscarriages." (PMID 38369498, 2024).
mitral valve prolapse (1 paper, 2019). A fairly common and often benign valvular heart disorder characterized by redundancy or hooding of mitral valve leaflets so that they prolapse into the left atrium, often causing mitral regurgitation. "Extending this model to patient-specific induced pluripotent stem cells recapitulates features of mitral valve prolapse and identified dysregulation of the SHH pathway." (PMID 31028265, 2019). "Here, the authors derive human pre-valvular endocardial cells (HPVCs) from iPSCs and show they can recapitulate early valvulogenesis, and patient derived HPVCs have features of mitral valve prolapse and identified SHH dysregulation." (PMID 31028265, 2019).
mood disorder (1 paper, 2025). A cognitive disorder a disturbance in which the person's mood is hypothesized to be the main underlying feature. "SHH, an essential regulator of neurogenesis and axonal targeting, has been implicated in mood disorders and could contribute to impaired neural plasticity in suicidal individuals." (PMID 40640508, 2025).
nasopharyngeal carcinoma (1 paper, 2021). A carcinoma arising from the nasopharyngeal epithelium. "In EBV-positive nasopharyngeal carcinomas (NPC) and EBV-infected epithelial cell lines, the virus can activate the HH signaling pathway through autocrine induction of SHH." (PMID 34422814, 2021).
nephronophthisis (1 paper, 2024). Progressive tubulointerstitial injury, inherited in an autosomal recessive pattern, caused by mutations in genes involved in ciliary function, which may result in an end stage renal failure. "Alterations of the SHH signaling pathway have been implicated in both developmental and degenerative instances of kidney disease, such as nephronophthisis and kidney fibrosis, supporting a role for disease modification." (PMID 38213489, 2024).
neuroectodermal tumors (1 paper, 2021). "The human poliovirus receptor CD155 gene acts as a transcriptional target of SHH and is activated by SHH in neuroectodermal tumors." (PMID 33494284, 2021).
neurofibroma (1 paper, 2023). An intraneural or extraneural neoplasm arising from nerve tissues and neural sheaths. "Our in-vitro and in-vivo data also demonstrated that SHH pathway activation is sufficient to drive malignant phenotype in Schwann cell and neurofibroma cell lines." (PMID 37164978, 2023).
odontogenic cyst (1 paper, 2025). A cyst in the jaw that arises from tissues of tooth development. "Indeed, aberrations in the MAPK, Sonic Hedgehog (SHH), and WNT/β-catenin pathways are well documented in odontogenic cysts and tumors, with BRAF, PTCH1, and CTNNB1 representing the most frequently altered genes." (PMID 41364259, 2025).
osteoma (1 paper, 2023). A benign, well-circumscribed, bone-forming neoplasm predominantly composed of lamellar bone.
papillary thyroid carcinomas (1 paper, 2021). "Others have also suggested that the MAPK and SHH pathways modulate DIO3 expression in papillary thyroid carcinomas and in an MTC cell line." (PMID 33435319, 2021).
pediatric cancers (1 paper, 2021). "MB, such as other pediatric cancers, is an illustrative example, two MB subgroups being very well distinguishable (SHH and WNT) and two others being far less characterized (G3 and G4)." (PMID 33889829, 2021).
periodontitis (1 paper, 2021). An acute or chronic inflammatory process that affects the tissues that surround and support the teeth. "It is found that the activation of Sonic Hedgehog (SHH) signaling pathway is related to the degree of inflammation in patients suffering from periodontitis." (PMID 34193016, 2021). "SHH is reported to potentially serve as a new therapeutic target for periodontitis and periodontal regeneration, the expression of which along with that of Gli1 in PDLSCs was examined in this study and was found to have an obvious increase after Pg-LPS stimulation." (PMID 34193016, 2021). "High expression of SHH was observed in gingival crevicular fluid of patients with periodontitis, indicating that SHH may participate in the inflammatory response of periodontitis." (PMID 34193016, 2021). "However, the regulatory role of CUL3,SHH/Gli, and NRF2 in periodontitis has not been reported so far." (PMID 34193016, 2021).
peripheral nerve injury (1 paper, 2020). Injury to a peripheral nerve. "In a rat model of cavernous nerve injured-induced erectile dysfunction, it has been suggested that SHH is essential in maintaining neuro-glial interactions and regulating the neural microenvironment under physiological conditions and peripheral nerve injury." (PMID 33266112, 2020). "SHH could promote axonal survival following peripheral nerve injury, by promoting the survival of injured neurons or via a neurotrophic effect (see Section 3.1.4), as similarly observed in the central nervous system following oxidative stress or oxygen-glucose deprivation for example." (PMID 33266112, 2020).
pressure ulcer (1 paper, 2023). "In this study, we were interested in the role and the underlying mechanism of SHH signaling in regulating angiogenesis properties of EPCs during pressure ulcers." (PMID 37815888, 2023). "We identified a crucial function of SHH signaling in promoting angiogenesis properties of EPCs to improve pressure ulcers healing by PI3K/AKT/eNOS signaling." (PMID 37815888, 2023). "Our data displays a critical role of SHH signaling in regulating angiogenesis of EPCs during pressure ulcers healing, uncovering the molecular mechanism of EPCs-mediated ulcers healing." (PMID 37815888, 2023). "In summary, we concluded that SHH signaling activated angiogenesis properties of EPCs to improve pressure ulcers healing by PI3K/AKT/eNOS signaling." (PMID 37815888, 2023). "Our finding provides new insight into the mechanism by which SHH signaling contributes to the EPCs-mediated pressure ulcers healing." (PMID 37815888, 2023). "Nevertheless, it is possible that other regulatory signaling cascades exist in SHH-regulated angiogenesis during pressure ulcer." (PMID 37815888, 2023). "Here, we aimed to explore the significance of SHH signaling in EPCs function during pressure ulcers." (PMID 37815888, 2023). "SHH signaling stimulated angiogenesis and improved pressure ulcers healing in the rat model." (PMID 37815888, 2023). "However, the association of SHH signaling with PI3K/AKT signaling in the regulation EPCs function and its role during pressure ulcer are still unclear." (PMID 37815888, 2023). "Next, we assess the function of SHH signaling in the pressure ulcers rat model." (PMID 37815888, 2023). "Moreover, the results from in vivo pressure ulcers rat model demonstrated that SHH pathway contributes to angiogenesis in the pressure ulcers rat model." (PMID 37815888, 2023). "SHH signaling has been found to regulate EPCs function, but the role of SHH in pressure ulcer remains unclear." (PMID 37815888, 2023). "SHH signaling may serve as the potential target for attenuating pressure ulcers." (PMID 37815888, 2023). "SHH signaling may be served as the potential targets for attenuating pressure ulcers." (PMID 37815888, 2023).
Pulmonary hypoplasia (1 paper, 2014). "WNT5A negatively regulates SHH expression in the chick lung and overexpression of WNT5A causes pulmonary hypoplasia." (PMID 24743779, 2014).
renal carcinoma (1 paper, 2023). A carcinoma arising from the epithelium of the renal parenchyma or the renal pelvis. "Therefore, we decided to investigate the immunoreactivity of the two major SHH pathway proteins, SHH and GLI1, as well as the expression of one of their important targets - VEGFA, in this type of renal cancer." (PMID 37964226, 2023).
renal hypoplasia (1 paper, 2023). Renal hypoplasia is a developmental anomaly in which one or both kidneys (unilateral or bilateral renal hypoplasia, respectively) have a deficit in the number of nephrons and may be small. "Numerous cases of CAKUT in patients carrying terminal deletions in the long arm of chromosome 7q32-36 (encompassing the SHH locus) have been reported with phenotypes including renal hypoplasia, renal dysplasia, ectopic kidney, duplex collecting system and VUR." (PMID 37675356, 2023).
respiratory failure (1 paper, 2025). The significant impairment of gas exchange within the lungs resulting in hypoxia, hypercarbia, or both, to the extent that organ tissue perfusion is severely compromised. "Mice with a loss function of hedgehog interacting protein, an antagonist of SHH pathway, die a few hours after birth due to respiratory failure." (PMID 39827090, 2025).
retinal tumours (1 paper, 2024). "Activation of SHH signalling in zebrafish CNS models led to increased tumorigenesis, demonstrating the oncogenic role of SMOA1 in brain and retinal tumours." (PMID 39568072, 2024).
schwannoma (1 paper, 2025). A benign, usually encapsulated slow growing tumor composed of Schwann cells. "Further, pathway analysis indicated the upregulation of VEGF, SHH and MEK pathways, in addition to mismatch-repair and DNA repair-related genes in SWN-schwannomas as compared to sporadic schwannomas." (PMID 40794298, 2025).
Sepsis (1 paper, 2025). Sepsis is defined as life-threatening organ dysfunction caused by a dysregulated host response to infection. "Although not yet directly implicated in sepsis, it may participate in the disease process by influencing immune-cell proliferation and the SHH/WNT signaling pathways." (PMID 41246299, 2025).
serous ovarian cancers (1 paper, 2020). "This analysis revealed an enrichment of SHH pathway genes, including GLI1, GLI2, HHIP, PTCH1, and PTCH2, in SSTs as compared to high-grade serous ovarian cancers and other sex cord-stromal tumors." (PMID 31896750, 2020).
silicosis (1 paper, 2020). Silicosis is a respiratory disease caused by breathing in (inhaling) silica dust. "The purpose of this study was to determine the effects of Kinesin family member 3A (KIF3A) on primary cilia and myofibroblast differentiation during silicosis by regulating Sonic hedgehog (SHH) signalling." (PMID 32042332, 2020). "Our previous study showed that activation of SHH signalling has a major role in silicosis." (PMID 32042332, 2020). "Recently, we reported a major role of the Sonic hedgehog (SHH) pathway in silicosis." (PMID 32042332, 2020).
Smith-Lemli-Opitz syndrome (1 paper, 2016). Smith-Lemli-Opitz syndrome (SLOS) is characterized by multiple congenital anomalies, intellectual deficit, and behavioral problems. "The underlying mechanism in Smith-Lemli-Opitz syndrome is a disturbed SHH-GLI signal transduction: cholesterol is essential to activate this pathway." (PMID 26822476, 2016).
steatosis (1 paper, 2019). Increased lipid within the cytoplasm of cells. "Notably, hepatic SHH expression correlated with histologic ballooning degeneration (rho = 0.62, p < 0.0001), steatosis grade (rho = 0.554, P < 0.001), Mallory-Denk bodies (rho = 0.54, P < 0.001), pericellular fibrosis (rho = 0.527, P < 0.001), and lymphocytic infiltration (rho = 0.435, P < 0.0002)." (PMID 30744560, 2019).
synovitis (1 paper, 2020). Inflammation of a synovial membrane. "To further assess the effect of SHH-JNK signaling on FLSs invasiveness in vivo, we employed a humanized synovitis animal model and FLSs were infected with AAV overexpressing SHH before implantation." (PMID 32670287, 2020).
teratoma (1 paper, 2022). A non-seminomatous germ cell tumor characterized by the presence of various tissues which correspond to the different germinal layers (endoderm, mesoderm, and ectoderm). "The extensive expression of SHH protein in PTCH1+/− teratoma and presence of apoptotic cells in PTCH1−/− teratoma also support the idea that apoptosis both in PTCH1+/− and PTCH1−/− teratomas are induced by a PTCH1-independent manner." (PMID 35618979, 2022).
type 2 diabetes (1 paper, 2019). "Logistic modeling indicates hepatic SHH expression and presence of type 2 diabetes as independent predictors of advanced fibrosis (defined as portal and pericellular fibrosis > 2: OR = 1.986, p = 0.01, and OR = 3.280, p = 0.03, respectively)." (PMID 30744560, 2019).
unstable angina (1 paper, 2020). "In this study, we examined the associations between polymorphisms in GP6 (rs1671152), PEAR1A (rs12566888), MRVI1 (rs7940646), PIK3CG (rs342286), JMJD1C (rs10761741), and SHH (rs2363910) and unstable angina." (PMID 33076381, 2020). "The results of this study suggest a lack of association between GP6 (rs1671152), PEAR1A (rs12566888), MRVI1 (rs7940646), PIK3CG (rs342286), JMJD1C (rs10761741), SHH (rs2363910), and unstable angina." (PMID 33076381, 2020).
Ventricular arrhythmia (1 paper, 2020). "In this context, targeting SHH signaling could then offer a promising cardioprotection both by limiting the infarct size but also by decreasing the early ventricular arrhythmias." (PMID 32226535, 2020).
vesicoureteral reflux (1 paper, 2021). Abnormal flow of urine from the urinary bladder back into the ureters. "Clinically, urinary tract malformations, such as ureteral duplication and ectopy, vesicoureteral reflux, bladder exstrophy are reported in human infants with mutations of SHH or its related signaling pathway genes." (PMID 35004540, 2021).